IL7R (interleukin 7 receptor)
Diseases named in the same sentence as IL7R in open-access papers (continued):
Sharing a sentence is not in itself a finding about the gene and the disease.
malignant pleural mesothelioma (1 paper, 2022). A malignant neoplasm that arises from mesothelial cells in the pleura and shows a diffuse growth pattern. "Tumor expression of interleukin‐7 receptor (IL‐7R) has been reported to be associated with poor prognosis in malignant pleural mesothelioma (MPM), a highly aggressive cancer." (PMID 36054746, 2022). "In this study, we aimed at evaluating the IL‐7R/IL‐7 pathway in malignant pleural mesothelioma (MPM)." (PMID 36054746, 2022).
mesothelioma (1 paper, 2022). A usually malignant and aggressive neoplasm of the mesothelium which is often associated with exposure to asbestos. "The objective of this study was to evaluate the IL‐7/IL‐7R pathway in mesothelioma using a collection of samples from patients." (PMID 36054746, 2022).
morbid obesity (1 paper, 2023). An excess of body weight, normally defined as an individual with a body mass index greater than 35 or a body weight greater than one hundred percent of ideal body weight. "Thus, blocking IL7-R signaling might provide a key therapeutic approach to impact survival of IL-7R expressing memory T cells, improving T cell homeostasis, and controlling inflammation in a state of morbid obesity." (PMID 37266430, 2023).
nasopharyngeal carcinoma (1 paper, 2021). A carcinoma arising from the nasopharyngeal epithelium. "Moreover, IL7R and other interleukin genes have been reported to be inhibited by miR-9, which may link inflammation with nasopharyngeal carcinoma." (PMID 34307154, 2021).
otitis media with effusion (1 paper, 2012). Otitis media associated with accumulation of fluid in the middle ear. "Therefore, a high percentage of T cells with IL-7R expression in children with otitis media with effusion may contribute to the maintenance of normal proportions in the subpopulations of adenoid T cells." (PMID 22382400, 2012). "The study objective was to assess the percentage of lymphocytes T (CD4+ and CD8+) with IL-7R (CD127 and CD132) expression in the group of children with hypertrophic adenoid in children with otitis media with effusion who suffer of 3 months’ duration." (PMID 22382400, 2012). "The aim of this study was to evaluate the percentage of lymphocytes T (CD4+ and CD8+) with IL-7R (CD127 and CD132) expression in hypertrophic adenoid in children suffering with otitis media with effusion for a duration of 3 months." (PMID 22382400, 2012). "The increased percentage of T lymphocytes with IL-7R expression (CD127 and CD132) in hypertrophic adenoid seems to influence the quantity of lymphocytes and upset the immunological function of tonsils which can influence the course of otitis media with effusion." (PMID 22382400, 2012).
primary progressive MS (1 paper, 2017). "This is consistent with a study demonstrating that the expression of IL-7R is decreased in patients with primary progressive MS." (PMID 28415697, 2017).
relapsed (1 paper, 2019). "Interleukin 7 (IL-7) and its receptor IL-7Rα promote T-ALL development and mutational activation of IL-7Rα associates with very high risk in relapsed disease." (PMID 30850736, 2019).
Salmonella Infections (1 paper, 2017). Infections with bacteria of the genus SALMONELLA. "In accordance with prior studies, our data demonstrate that probiotic LGG attenuated the upregulation of intestinal IL-7 and IL-7Rα expression induced by Salmonella infection, thereby contributing to the amelioration of intestinal inflammation." (PMID 28770173, 2017).
spondyloarthropathies (1 paper, 2019). "Synovial fluid-derived monocytes from patients with spondyloarthritis are enriched for IL7R+ cells with a unique transcriptional profile that overlaps with IL-7-induced gene sets." (PMID 31594933, 2019). "We further demonstrate that IL7R-expressing monocytes are responsive to IL-7 with a distinct expression profile that significantly overlaps ex-vivo IL7R+ monocytes from the joints of patients with spondyloarthropathies." (PMID 31594933, 2019).
synucleinopathy (1 paper, 2025). A neurodegenerative disease that is characterized by the abnormal accumulation of aggregates of alpha-synuclein protein in neurons, nerve fibers or glial cells. "Our observations at gene level, such as upregulation of chemokine and interferon response genes CCL2, IRF7, IL7R, and the immunomodulatory checkpoint gene VSIR, further reflect the complex immune environment within synucleinopathy appendixes." (PMID 41279937, 2025).
vitamin D deficiency (1 paper, 2020). A nutritional condition produced by a deficiency of VITAMIN D in the diet, insufficient production of vitamin D in the skin, inadequate absorption of vitamin D from the diet, or abnormal conversion of vitamin D to its bioactive metabolites. "We found a significant association between vitamin D deficiency and three SNPs of the IL7R gene, namely rs987107 (P-value = 0.047), rs3194051 (P-value = 0.03), and rs1494571 (P-value = 0.036), in addition to two SNPs of CD40, namely rs1883832 and rs6074022 (P-value = 0.049 for both)." (PMID 32111053, 2020).
Vogt-Koyanagi-Harada disease (1 paper, 2025). A bilateral, chronic, diffuse granulomatous panuveitis typically characterized by serous retinal detachment and frequently associated with neurological (meningitis), auditory, and dermatological alterations. "In a subset of chronic uveitis patients (Vogt-Koyanagi-Harada disease), RNAseq analysis on the peripheral blood cells revealed that the gene for IL-7R is one of the highly expressed molecules in effector-memory CD4+ T cells." (PMID 40323267, 2025).
X-linked SCID (1 paper, 2019). "At variance with X-linked SCID and JAK3 deficiency, where B cells are genetically impaired in their capacity to respond to IL-21 and differentiate into antibody-secreting cells, IL7R-deficient B cells are functional, as long as T cell help is provided." (PMID 31440487, 2019).
tumor (345 papers, 2006 to 2026). "Interleukin-7 (IL-7), acting via the IL-7 receptor (IL-7R), plays a significant role in tumor progression, is closely associated with a poor prognosis for patients with PC, and is associated with MMP-3 and MMP-7 expression." (PMID 40001606, 2025). "The activation of the IL7R-JAK-STAT pathway is linked to alterations in the tumor microenvironment, affecting immune cell infiltration and activity." (PMID 40408005, 2025). "We observed expression of tertiary lymphoid structure (TLS)-associated gene signatures including CD79A, CXCL8, and IL7R (interleukin-7 receptor) which supports the presence of well-organized TLS within the tumor microenvironment." (PMID 40950184, 2025). "DIABLO (permutation test, p < 0.005) identified 15 transcripts in the CD20+ tumor cells (AOIs) to be positively associated with T-cell-rich MCLs, including IL7R, CD47, CD80, CD84 and NLRC5." (PMID 39001353, 2024). "We also observed the expression of IL-7 and IL-7R in various mouse and human cell types and tumor tissues, which suggests that targeting the IL-7/IL-7R pathway presents both an opportunity and a risk for cancer patients." (PMID 38424167, 2024). "This protein encoded by IL7R plays a critical role in inhibiting tumor growth by modulating the proportion of immune infiltrating cells within the tumor’ s immune microenvironment." (PMID 39911484, 2024). "High IL-7R expression in tumor nests was associated with the levels of TAM and CAF infiltration and tended to be associated with poor prognosis in patients with ESCC." (PMID 36672342, 2023). "In this independent cohort, high IL-7R expression was associated with significantly longer tumor-specific survival (undefined vs. 678 d, P = 0.02, Log-rank test) compared with the IL-7Rlo group." (PMID 37459511, 2023). "IL7R is associated with the risk of NSCLC, and IL7R deficiency induces an increase in tumor-infiltrating regulatory T cells." (PMID 36358600, 2022). "Among them, cluster 5 exhibited a more active profile due the high expression of Cd40Ig gene but at the same time a higher expression of Il7r gene that encodes for a receptor whose ligand was related to tumor progression in γδ T cells." (PMID 35260564, 2022). "In a previous study using immunohistology, it was shown that high IL‐7R expression in MPM tumor was associated with worse outcomes." (PMID 36054746, 2022). "Studies have shown that patients with high tumor expression levels of interleukin-7 receptor (IL-7R) are associated with poor prognosis and upregulation of regulatory T cells (T regs)." (PMID 36139575, 2022). "This group observed that stromal FoxP3/CD3 ratio, tumor IL-12Rβ2, and tumor IL-7R were associated with recurrence." (PMID 34880292, 2021). "The expression levels of CXCL12 and IL7R significantly correlated with the construction of the tumor microenvironment and somatic mutations, and they are identified as potential diagnostic and therapeutic targets in the LIHC." (PMID 33344233, 2020). "Several authors have also reported that IL-7R expression in lung, breast or prostate cancer cells is associated with tumor aggressiveness, lymphovascular invasion and lymphangiogenesis." (PMID 28878234, 2017). "Studies have shown that interleukins and their receptors are closely associated with tumor metastasis; for example, IL-3 and IL-7R in different modules can promote both the proliferation and metastasis of tumors." (PMID 28628609, 2017). "In the first part of this study, we observed that IL-7R expression in both malignant lymphoid cells and metastatic solid tumor cells increased cell growth and survival activity and was associated with tumor aggressiveness." (PMID 28878234, 2017). "Next, we explored if upregulation of IL-7Rα is functionally important for combination therapy-induced tumour rejection by inoculating Il7r−/− mice, deficient of IL-7Rα with MB49 tumour cells, followed by combination therapy." (PMID 27498556, 2016).
tumor (continued). "Provided the relatively low incidence of the single gene mutations, clonal mutations (detected in >20% of tumor population) were grouped into the JAK/STAT (IL7R, JAK2, JAK1, CRLF2 mutations and CRLF2-rearrangements) and RAS/RTK (FLT3, KRAS, NRAS) pathways." (PMID 26883104, 2016). "High expression of tumor IL-7R is associated with worse outcome in patients with stage I lung adenocarcinoma." (PMID 25955647, 2015). "Elevated IL7R expression was associated with decreased overall survival (OS), confirming the existing literature linking IL7R to immune responses, particularly in the context of tumor biology and T cell dynamics." (PMID 40165301, 2025). "Furthermore, these immune cells in TME underwent transcriptional reprogramming, including CD8 + T subgroups of CCR7 + and IL7R+, as well as M2-like monocyte subgroups expressing tumor-associated signature genes, like CCR7, SGKI, and RPL31." (PMID 37221625, 2023). "The initial EMC may have been driven by SNPs in MYO18B, TRIM37, and IL7R; or loss of tumor suppressor genes on chromosome 10q." (PMID 39086683, 2023). "Moreover, pathways enriched in CCR7 + and IL7R + CD8 + T cell subgroups were associated with tumor proliferation and progression, tumor metastasis, and immunosuppression." (PMID 37221625, 2023). "Mutations in IL-7R in our primary tumor and lung metastasis may represent impaired IL-7 signaling in the tumor immune response." (PMID 39086683, 2023). "Transcriptional alterations in oncogenes and tumor suppressors may potentiate or collaborate with the effects of IL7R mutation." (PMID 35581375, 2022). "IL7R was previously reported to be amplified in various cancers, with the function of mediating potential tumor promotion, and high levels of IL-7R may be associated with poor prognosis." (PMID 35785159, 2022). "Transcriptional alterations in oncogenes and tumor suppressors may also potentiate or collaborate with the effects of IL7R mutation." (PMID 34907175, 2021). "In addition, restricted proportion and function of naive T cells by abnormally elevated IL7R can subsequently lead to a reduced activator T cells of functional immune response, underlying another potential mechanism of tumor immune evasion." (PMID 34159752, 2021). "Importantly, based on our data for 7 Ba/Sq samples, we were able to identify higher enhancer activity associated with potential key genes in Basal tumour biology, including cell surface receptors (IL7R, OSMR, EGFR, MET) and transcriptional regulators (BNC2, HMGA2, KLF7, NR3C1)." (PMID 36944729, 2023). "The other four genes not previously discovered to be correlated with the outcome of CM may likewise be crucial for the development of tumor, which include the interleukin receptor encoding gene IL7R, cytokine receptor FLT3, complement component C1QC, histocompatibility complex HLA-DRB5." (PMID 35300397, 2022). "In primary HGSOC, the recurrent tumor-specific DEG IL7R exhibited a positive correlation with AMBP and HDGF and a negative correlation with FEN1, LRRC25, RIGI, and TBL1X (p < 0.05)." (PMID 41596598, 2026). "In recurrent HGSOC, the recurrent tumor-specific DEGs IL7R, IRF8, and PTPRC displayed significant correlations with seven proteins." (PMID 41596598, 2026). "Dynamic tracking at the tumor-stroma interface demonstrated that IL7R knockdown shortened the migration distance of tumor cells from the printing boundary into the stroma." (PMID 41360767, 2025). "The mechanisms mediated by IL-7R exert dual pro-tumor effects: promoting tumor cell proliferation and metastasis, as well as remodeling the immune microenvironment." (PMID 41360767, 2025). "Tumor-infiltrating CD4+ T28zT2 T cells are enriched with TCF-1+IL7R+ memory-like T cells, express NKG2D, and downregulate T cell exhaustion markers, including PD-1 and LAG3." (PMID 40107245, 2025). "These IL7R-knockdown cells were co-bioprinted with stromal components to construct a 3D tumor-stroma model." (PMID 41360767, 2025).
tumor (continued). "The regulatory role of IL-7 in immune cells—mediated by its binding to the receptor IL7R—has been extensively studied, and emerging evidence indicates that IL-7/IL7R signaling modulates tumor-immune interactions." (PMID 41360767, 2025). "Among the transcripts selectively up-regulated by apyrase administration, we detected Il7r, which characterizes a stemlike and tumor-responsive CD8 T cell population capable of sustaining the therapeutic response induced by ICB." (PMID 41042869, 2025). "The immune infiltration analysis also shows that IL7R gene is negatively correlated with the tumor purity in LIHC samples in the immune cells CD8 + and CD4 + T cells." (PMID 40408005, 2025). "This study further demonstrated that the expression of CXCL1 is regulated by IL-7R signaling: tumor cells with high IL-7R expression upregulate CXCL1 to drive the polarization of immunosuppressive macrophages." (PMID 41360767, 2025). "The results confirmed that the mRNA expression levels of Cxcl1 and Cxcl2 were decreased in Il7r-KO tumor cells, while the expression of Cxcl3 remained unchanged." (PMID 41360767, 2025). "The IL7R expression differences in spleen-derived T cells and tumor-infiltrating CD3+ cells were probably due to different original microenvironments." (PMID 40107245, 2025). "By employing 3D bioprinted co-culture systems and mouse models, we showed that the knockdown or knockout of IL7R inhibits tumor progression and intraperitoneal dissemination." (PMID 41360767, 2025). "KEGG pathway enrichment analysis identified significant activation of the HIF-1 signaling pathway in TAMs from the TME of mice inoculated with Il7r-WT cells; this pathway is crucial for the immunosuppressive function of macrophages and tumor progression." (PMID 41360767, 2025). "Previous studies have shown that IL7R promotes tumor cell survival by activating the JAK-STAT pathway." (PMID 41249788, 2025). "Immunofluorescence staining revealed that the regions with IL7R-expressing tumor were specifically enriched with CD68+CD206+ macrophages." (PMID 41360767, 2025). "For instance, CD27-based CAR T cells have demonstrated higher antitumor activity and increased survival in tumor-bearing mouse models, upregulating IL-7Rα expression while downregulating PD-1 expression." (PMID 40181405, 2025). "To enhance functional persistence in a tumor-localized manner, we expressed the transgenic IL-7 cytokine and receptor (IL-7Rα) in respective CAR products." (PMID 40808942, 2025). "The present study reveals that upon activation in tumor cells, IL7R promotes CXCL1 secretion by facilitating the nuclear translocation of NF-κB, which then binds to the CXCL1 promoter." (PMID 41360767, 2025). "We further quantified the differences in cell type proportions between tumor tissues of mice inoculated with Il7r-KO cells and those with Il7r-WT cells." (PMID 41360767, 2025). "By deleting Lrp10 in mice, we have discovered that Lrp10 prevents accumulation of naive and memory CD8 T cells in secondary lymphoid organs, limits IL7R expression, suppresses T-cell homeostatic expansion, and impairs anti-tumor immune responses." (PMID 38956225, 2024). "This study shows that Lrp10 prevents accumulation of peripheral CD8 T cells, suppresses IL7R expression to limit homeostatic expansion, and impairs anti-tumor immune responses." (PMID 38956225, 2024). "We also investigated the immune microenvironment, finding high expression of IL7 in tumor cells and high IL7R expression in tumor-infiltrating T cells, suggesting that immune interactions also play a role in local tumor invasion and progression." (PMID 39093440, 2024). "Monocyte scores showed a significant positive correlation with the expression of TM cell marker genes including SELL, CCR7, and IL7R in most tumor types." (PMID 38386350, 2024).